HMGA2 (high mobility group AT-hook 2)
Diseases named in the same sentence as HMGA2 in open-access papers (continued):
Sharing a sentence is not in itself a finding about the gene and the disease.
giant cell tumor (1 paper, 2022). A benign, intermediate, or malignant tumor that arises from the bone or soft tissue. "This HMGA2::NCOR2 fusion has recently been described in a series of 6 “giant cell tumors of soft tissue” and in a series of 6 “osteoclastic giant cell-rich tumors of bone”." (PMID 36439507, 2022). "RNA-seq led to the reclassification of four “HMGA2::NCOR2 giant cell tumors”." (PMID 36439507, 2022).
giant cell tumor of soft tissue (1 paper, 2024). A painless, well circumscribed tumor arising in soft tissue, usually of the upper and lower extremities. "The authors reported a series of six cases similar to giant cell tumor of soft tissue (GCTST) but with a distinct predilection for appearing in young females, demonstrating keratin expression, and harboring a high mobility group AT-hook 2 (HMGA2)–nuclear receptor corepressor 2 (NCOR2) fusion." (PMID 38792018, 2024).
hyperandrogenism (1 paper, 2023). Excessive secretion of androgens from the adrenal glands or gonads. "HMGA2 has also been significantly associated with both hyperandrogenism and oligo/amenorrhea in women with PCOS in Saudi Arabia." (PMID 37223019, 2023).
Hyperinsulinemia (1 paper, 2023). An increased concentration of insulin in the blood. "Thus, although as a single variant genetic test HMGA2 may be useful for breeding decisions regarding height, it would not provide enough information to quantify a patient's total genetic risk for basal hyperinsulinemia." (PMID 37148171, 2023).
Hypoglycemia (1 paper, 2024). A decreased concentration of glucose in the blood. "Feeding difficulties, poor weight gain, and hypoglycemia frequently seen in human patients may be countered by targeted manipulation of genetic targets and pathways affiliated with HMGA2-induced adipocyte formation." (PMID 38516887, 2024).
intestinal cancer (1 paper, 2015). "Analysis of both mouse and human intestinal cancer specimens reveals that stem cell markers were significantly associated with loss of Let-7 miRNA expression, and that a number of Let-7 targets were elevated, including Hmga1 and Hmga2." (PMID 26244988, 2015). "In aggregate, we conclude that Let-7 depletion drives a stem cell phenotype and the development of intestinal cancer, primarily via Hmga2." (PMID 26244988, 2015).
ischemia (1 paper, 2019). A hypoperfusion of the BLOOD through an organ or tissue caused by a PATHOLOGIC CONSTRICTION or obstruction of its BLOOD VESSELS, or an absence of BLOOD CIRCULATION. "Taken together, through direct targeting on HMGA2, Let-7d-3p inhibited apoptosis and protected the cells against ischemia injury." (PMID 30934671, 2019).
ischemic stroke (1 paper, 2022). A stroke disorder caused by obstruction of blood flow to the brain, due to thrombotic (local blood clot formation) or embolic (due to a blood clot or other material traveling from another site) event. "Collectively, the current study for the first to link the therapeutic effect of rTMS on ischemic stroke with microglial polarization and reveal the possible molecular mechanism was associated with let-7b-5p/HMGA2/NF-κB pathway." (PMID 35927640, 2022). "High-frequency rTMS could alleviate ischemic stroke injury through inhibiting M1 microglia polarization via regulating let-7b-5p/HMGA2/NF-κB signaling pathway in MCAO models." (PMID 35927640, 2022).
lactotroph adenomas (1 paper, 2020). "However, according to the current evidence that has been collected on genes in the HMGA family, only HMGA2 has a direct causal role in human pituitary tumorigenesis because it is amplified or rearranged in human lactotroph adenomas." (PMID 33574795, 2020). "HMGA2 has been shown to be rearranged and amplified in lactotroph adenomas, and transgenic mice with Hmga2 overexpression develop PAs with prolactin and GH secretion." (PMID 33574795, 2020).
large cell carcinoma (1 paper, 2016). A malignant epithelial neoplasm composed of large, atypical cells. "Patients with large cell carcinomas and low expression of the HMGA2 protein also had a better outcome (log rank test, p = 0.014)." (PMID 26858029, 2016).
metastatic prostate carcinoma (1 paper, 2024). A carcinoma that arises from the prostate gland and has spread to other anatomic sites. "This suggests that HMGA2 plays a specific role in the development of resistance to enzalutamide in metastatic prostate cancer (mPCa)." (PMID 39123360, 2024). "Additionally, alisertib may be an effective treatment for patients with high HMGA2 levels, offering a new potential therapeutic strategy for managing metastatic prostate cancer." (PMID 39123360, 2024).
Müllerian adenosarcoma (1 paper, 2023). "Meanwhile, MDM2, CDK4, HMGA2, and GLI1 gene amplifications are common molecular events in Müllerian adenosarcoma, often seen in patients with SO." (PMID 37810911, 2023).
myeloid leukemia (1 paper, 2021). A clonal proliferation of myeloid cells and their precursors in the bone marrow, peripheral blood, and spleen. "Moreover, HMGA2 plays a crucial role in myeloid differentiation and HMGA2 silencing induces the differentiation of myeloid leukemia cells." (PMID 34732703, 2021).
myeloproliferative neoplasm (1 paper, 2024). A clonal hematopoietic stem cell disorder, characterized by proliferation in the bone marrow of one or more of the myeloid (i.e., granulocytic, erythroid, megakaryocytic, and mast cell) lineages. "The overexpression of Hmga2 induced a myeloproliferative phenotype in a transgenic mouse, and drove the development of myeloproliferative neoplasms induced by the JAK2V617F mutation or Tet2 deletion in mouse models." (PMID 38811851, 2024).
papillary serous carcinoma (1 paper, 2013). "The immunohistochemistry results indicate that HMGA2 overexpression is an early event in the tumorigenesis of high-grade papillary serous carcinoma." (PMID 23251297, 2013).
papilloma (1 paper, 2017). A benign epithelial neoplasm that projects above the surrounding epithelial surface and consists of villous or arborescent outgrowths of fibrovascular stroma. "Importantly, we also demonstrated that and upon transformation to skin papillomas and carcinomas in vivo, Hmga2 initially relocated throughout the cell with still some cell membrane associated Hmga2 in papillomas, but relocated to the nucleus in carcinomas." (PMID 28415789, 2017). "In addition, KI67 positive cells in papillomas were significantly decreased in the panobinostat treated group, demonstrating that Panobinostat also prevented translocation of Hmga2 in vivo in developing tumors, which was associated with a decreased proliferation of transformed cells." (PMID 28415789, 2017). "Our findings demonstrate that upon program of benign papilloma to malignant cSCC of skin tumorigenesis, Hmga2 translocates in a ROCK-dependent manner from the membrane to the nucleus, where it serves as an autoregulatory transcription factor, causing cell transformation." (PMID 28415789, 2017). "More than 50% of the cells in the papillomas of vehicle control treated mice contained nuclear Hmga2, while in panobinostat treated mice, there were either no or lower levels of Hmga2 protein in the nucleus, and in some cells Hmga2 was detected in the membrane." (PMID 28415789, 2017).
Parkinson disease (1 paper, 2023). A progressive degenerative disorder of the central nervous system characterized by loss of dopamine producing neurons in the substantia nigra and the presence of Lewy bodies in the substantia nigra and locus coeruleus. "Hmga2 is a target of let-7b-5p, and the let-7b—Hmga2 axis regulates NSC senescence and has been implicated in cell apoptosis in Parkinson’s disease." (PMID 37108729, 2023).
prostatic intraepithelial neoplasia (1 paper, 2015). "This was observed in a mouse model of prostatic intraepithelial neoplasia, where overexpression of Hmga2 in cancer-associated fibroblasts enhances expression of the Wnt ligands Wnt2, Wnt4, and Wnt9b, concomitant with enhanced Wnt signaling and nuclear β-catenin in adjacent neoplastic epithelium." (PMID 26244988, 2015).
pulpitis (1 paper, 2025). Inflammation of the dental pulp. "Another study revealed that let‐7c‐5p promoted anti‐inflammatory and pro‐osteogenic effects in DPSCs by restoring the proliferation and osteogenic differentiation impaired by pulpitis through the inhibition of high mobility group A2 (HMGA2)/phosphatidylinositol 3‐kinase (PI3K)/Akt signalling." (PMID 40497413, 2025).
rectum cancers (1 paper, 2019). "Because HMGA2 was commonly overexpressed in gastrointestinal cancers, we focused on esophagus, stomach, colon, and rectum cancers." (PMID 31581665, 2019). "Our results suggested that HMGA2 expression did not predict patients’ prognosis (overall and disease-free survivals) based on TCGA datasets (esophagus, stomach, colon, and rectum cancers)." (PMID 31581665, 2019).
retinal ischemia (1 paper, 2025). A ischemic disease that involves the retina. "Employing snRNA‐seq post‐MCAO‐induced retinal ischemia (RI), this study revealed a novel Hmga2‐high Müller cell subpopulation." (PMID 40884260, 2025).
silicosis (1 paper, 2019). Silicosis is a respiratory disease caused by breathing in (inhaling) silica dust. "To further analyze the regulation of HMGA2 on EMT and silicosis, we used siRNA targeting HMGA2 to reduce the expression of HMGA2." (PMID 35519367, 2019). "qRT-PCR revealed the down-regulation of let-7d and the concomitant increase of HMGA2 in silica-treated mice, thus confirmed their potential relationship in silicosis in vivo." (PMID 35519367, 2019). "In the present study, we established a mouse silicosis model to analyze the expression of let-7d and HMGA2." (PMID 35519367, 2019). "The down-regulation of let-7d and the high-regulation of HMGA2 were also observed in silicosis." (PMID 35519367, 2019). "To detect whether let-7d and its target HMGA2 were involved in silica-induced EMT, we established a silicosis mouse model and found that let-7d was down-regulated and HMGA2 was up-regulated in the silica-treated group." (PMID 35519367, 2019).
skin carcinoma (1 paper, 2017). "Ex vivo culture of KCs and development of skin carcinomas in DMBA and TPA mouse models was associated with translocation of the Hmga2 protein from the membrane into the nucleus, where Hmga2 induced its own expression by binding to the Hmga2 promoter." (PMID 28415789, 2017). "Whether Hmga2 is involved in skin cancer development has not yet been addressed." (PMID 28415789, 2017).
skin papilloma (1 paper, 2017). A benign papillary neoplastic growth on the skin composed of epithelial cells and a fibrous stalk. "Interestingly, when Hmga2 staining was performed on mouse skin papilloma tissue, Hmga2 was also found in the nucleus in most cells while Hmga2 was cell membrane associated in a few cells." (PMID 28415789, 2017).
Splenomegaly (1 paper, 2016). Abnormal increased size of the spleen. "It has been shown that transgenic mice carrying a 3'UTR-truncated Hmga2 cDNA showed proliferative hematopoiesis, erythropoietin-independent erythroid colony formation, as well as hypercellular bone marrow and splenomegaly." (PMID 27861570, 2016).
sterility (1 paper, 2022). "Detailed analyses revealed that inactivation of Hmga2 resulted in a complex phenotype with growth retardation in prenatal and postnatal development, penile prolapse, sterility in both males and females, and altered behavior." (PMID 34878116, 2022).
testicular germ cell tumours (1 paper, 2020). "The expression of HMGA2 distinguishes between different types of post-pubertal testicular germ cell tumours, thus, indicating that HMGA2 has a role in germ cell proliferation, which could affect testicular development in bulls." (PMID 32787790, 2020).
thymolipoma (1 paper, 2021). "In one case, a translocation involving the High Mobility Group AT-Hook 2-HMGA2 gene on chromosome 12q15 was detected, supporting the theory that thymolipoma is a neoplasm of thymic fat." (PMID 34439210, 2021).
urothelial carcinoma (1 paper, 2025). A malignant neoplasm derived from the transitional epithelium of the urinary tract (urinary bladder, ureter, urethra, or renal pelvis). "The significant increase of HMGA2 positivity from non-invasive (5.9–18.2% positive) to invasive urothelial carcinomas (35.9–43.2%) is another example where HMGA2 upregulation is linked to cancer progression." (PMID 40518465, 2025).
uterine sarcoma (1 paper, 2025). "RAD51B fusion uterine sarcoma is not a morphological diagnosis, but rather a mixture of recently recognized subset of uterine sarcomas characterized by gene fusions involving RAD51B and various partner genes, most commonly HMGA2 or NUDT3." (PMID 41463261, 2025).
tumor (521 papers, 2003 to 2026). "Increased HMGA2 expression is closely linked to tumor advancement, unfavorable prognosis, and inadequate response to therapeutic interventions." (PMID 41769690, 2026). "The biological importance of HMGA2 is further supported by significant associations between HMGA2 overexpression and features of tumor progression in several tumor types." (PMID 40518465, 2025). "KEGG enrichment analysis showed that HMGA2 was associated with tumor pathways such as cell cycle regulation, cell proliferation, Hippo signaling pathway, and TGF−beta signaling pathway." (PMID 40703517, 2025). "To illustrate the diagnostic and clinical challenges posed by HMGA2-altered neoplasms neoplasms, we first present an index case involving an HMGA2 alteration and MDM2 co-amplification." (PMID 40338436, 2025). "Associations between high levels of HMGA2 and poor prognosis and/or unfavorable tumor phenotype were found in various tumor entities." (PMID 40518465, 2025). "Then, GO and KEGG pathway analyses were conducted, consistently revealing the association of HMGA2 with cell proliferation and tumor related pathways." (PMID 40703517, 2025). "At the genetic level, knocking out the HMGA2 gene in cancer cells can induce apoptosis, cause cell cycle arrest, and inhibit tumor migration and invasion." (PMID 39591457, 2024). "A study of 41 patients receiving curative intent surgery for pCCA found that HMGA2-positive nuclei (i.e., ≥20% HMGA2 staining) in resected tumour specimens was significantly associated with poorer 5-year OS of 32.5% versus 62.5% upon univariable analysis." (PMID 38398089, 2024). "HMGA2-positive tumours were also associated with lower DFS upon univariable and multivariable analyses in this study (HR = 3.246, 95% CI 1.296–8.133, p = 0.012)." (PMID 38398089, 2024). "CRABP2 and HMGA2 had the highest expression in ChRCCdediff and have been previously implicated in tumor aggressiveness and EMT." (PMID 38775158, 2024). "Overexpression of HMGA2 is associated with numerous cancers, possibly by promoting epithelial-to-mesenchymal transition, which in turn is associated with tumour dissemination." (PMID 38398089, 2024). "They observed that HMGA2 expression was associated with poor tumor differentiation in patients with PDAC cases and increased age in patients with AAC." (PMID 37787719, 2023). "In the univariate analysis, the HMGA2 protein expression was found to increase the risk of disease-related death in the entire neoplasia cohort (P = .016)." (PMID 37787719, 2023). "In the neoplasia cohort, E-cadherin showed a partial loss in 24 and complete loss in 3 in HMGA2-positive cases (n = 27)." (PMID 37787719, 2023). "After systemic administration of aptamer-miRNA chimera in immune-deficient mice with an A549 NSCLC-derived tumor, there was downward adjustment of the target 7g HMGA2, as well as inhibition of tumor growth." (PMID 35269947, 2022). "Loss of let-7 enhances oncogene RAS and HMGA2 expression, which also promotes ”stemness” by repressing self-renewal and promoting differentiation in tumor-initiating cells." (PMID 35454929, 2022). "The xenograft tumor of HMGA2-deficient cells demonstrated a retarded growth pattern compared with the control." (PMID 35439951, 2022). "These outcomes signposted that circTRIM28 deficiency repressed tumor growth via miR-409-3p/HMGA2 axis." (PMID 36180890, 2022). "For example, HMGA2 has been implicated as a driver of tumor metastasis; however, hsa-miR-302a-5p is the powerful post-transcriptional regulator of HMGA2." (PMID 36101384, 2022). "Our results revealed a strong association between HMGA2 expression in tumor cells and CD68 expression in the stroma." (PMID 34976223, 2022). "Our results from human CRC specimens also revealed a strong positive association between HMGA2 expression in tumor cells and CD68 expression in the stroma." (PMID 34976223, 2022).